REN (renin)
Diseases named in the same sentence as REN in open-access papers (continued):
Sharing a sentence is not in itself a finding about the gene and the disease.
Adrenal insufficiency (20 papers, 2014 to 2026). Insufficient production of steroid hormones (primarily cortisol) by the adrenal glands. "Therefore, the diagnosis of adrenal insufficiency has to largely rely on the measurement of baseline morning cortisol levels, whilst ACTH and renin levels can help to distinguish the rare cases of primary adrenal insufficiency from those with ACTH deficiency." (PMID 36884258, 2023). "Our patient did have normal renin and aldosterone levels after developing adrenal insufficiency, likely related to the lower affinity of the osilodrostat for the CYP11B2 enzymatic blockade than for the CYP11B1 enzyme." (PMID 40303510, 2025). "In common with previous work, and considering the various conditions included in this study, renin measurements are helpful for measuring the degree of mineralocorticoid insufficiency in all forms of adrenal insufficiency." (PMID 38165389, 2024). "Overall, the decision to adjust fludrocortisone dose in this cohort of children with adrenal insufficiency was better supported by the biochemical parameters when based on renin concentration results and clinical status." (PMID 38165389, 2024). "Plasma adrenocorticotropic hormone levels were elevated with low serum cortisol levels and high plasma renin activity, which were suggestive of adrenal insufficiency." (PMID 37745698, 2023). "For the patient with primary adrenal insufficiency only, therequested tests were skull and full spine MRI, electroencephalogram, neurologicaltests, and levels of sodium, potassium, renin, adrenocorticotropic hormone (ACTH),cortisol and VLCFA." (PMID 31241695, 2019). "Adrenal workup allowed us to establish a diagnosis of adrenal insufficiency (AI) due to autoimmune adrenalitis, considering findings of a low cortisol and positive 21-hydroxylase antibodies (21OH-Abs), as well as high serum renin and adrenocorticotropic hormone (ACTH)." (PMID 38034146, 2023). "High plasma renin activity and norepinephrine concentration and also a high probability of hepatorenal syndrome type 1 have been shown in cirrhotic patients with relative adrenal insufficiency." (PMID 28812008, 2017). "Tertiary adrenal insufficiency generally has a less dramatic presentation than primary adrenal insufficiency; acute circulatory collapse seems rare, because aldosterone levels, which are controlled pre-dominantly by the renin-angiotensin system, are preserved." (PMID 25608777, 2014). "While biochemical markers such as low cortisol and aldosterone levels, along with elevated ACTH and plasma renin activity, may suggest adrenal insufficiency, definitive diagnosis requires genetic confirmation through identification of mutations in the STAR gene." (PMID 41502797, 2026). "Based on our current knowledge of adrenal insufficiency, we believe that MC replacement should take into account renin, cortisol, ACTH, sodium, potassium, and blood pressure, as well as any individual characteristics (such as other treatments or comorbidities) that may affect these measures." (PMID 39416427, 2024). "Earlier records noted low cortisol, elevated renin and ACTH, subnormal aldosterone, and 17‐hydroxyprogesterone > 0.4 nmol/L (normal > 1 nmol/L), supporting primary adrenal insufficiency." (PMID 41502797, 2026). "This is among the first reported cases of unprovoked isolated adrenal insufficiency with abnormal cortisol, ACTH, DHEA-S levels, and normal renin and aldosterone levels." (PMID 39525095, 2024). "Although primary adrenal insufficiency is rare, if the ACTH or renin level was elevated then mineralocorticoid replacement with fludrocortisone is required." (PMID 36884258, 2023). "Screen all boys and men for adrenal insufficiency with early morning cortisol, ACTH, plasma renin, and serum electrolytes." (PMID 36175155, 2022). "The exact time of renin measurement was not known, but this does not seem to be critical as renin concentration is stable over 24 hours in patients with adrenal insufficiency." (PMID 39416427, 2024).
Adrenal insufficiency (continued). "In our case, the adrenal insufficiency diagnosis was highly probable, given the clinical course, the biological tests performed, and the sequence of CT images, although the workup should ideally have included ACTH, renin and aldosterone levels." (PMID 25645253, 2015). "Unlike secondary adrenal insufficiency, mineralocorticoid deficiency might be caused by PAI, and plasma renin and aldosterone levels could be useful for differential diagnosis." (PMID 40227797, 2025). "Treatment adherence could not be assessed, although it could influence renin measurements, especially in patients with multiple daily intakes: In a recent study, 32% of 41 patients with adrenal insufficiency were considered to be noncompliant." (PMID 39416427, 2024).
dilated cardiomyopathy (20 papers, 2017 to 2026). Cardiomyopathy which is characterized by dilation and contractile dysfunction of the left and right ventricles. "Pathway analysis shed light on several significant pathways, including Salivary secretion, Dilated cardiomyopathy, Renin secretion, among others, offering insights into the underlying molecular mechanisms of lung cancer." (PMID 38066059, 2023). "There are limited experimental studies exploring the direct effect of renin activity inhibition in dilated cardiomyopathy." (PMID 31404946, 2019). "In dogs with dilated cardiomyopathy, increases in the activities of renin and aldosterone, atrial natriuretic peptide, vasopressin, cortisol, catecholamines, nitrates, and nitrites, which are the end products of nitric oxide, are seen." (PMID 31749587, 2019). "We examined the significance of elevated plasma renin activity in a translationally-relevant model of dilated cardiomyopathy (DCM), which replicates the progressive stages (A–D) of human HF." (PMID 31404946, 2019). "However, a low-sodium diet (LSD) activates the classical renin-angiotensin-aldosterone system (RAAS), which may adversely affect HF progression and mortality in patients with dilated cardiomyopathy (DCM)." (PMID 33919841, 2021).
fibrosis (20 papers, 2013 to 2025). the formation of excess fibrous connective tissue in an organ or tissue in a reparative or reactive process. "An upregulated renin–angiotensin–aldosterone system causes atrial fibrosis and electrical remodeling, increasing the risk of AF." (PMID 34148488, 2021). "Such is the case of the autonomic nervous system, the renin-angiotensin-aldosterone system, and other less acknowledged routes, namely fibrosis or heart strain, and stretching." (PMID 37240672, 2023). "Administration of GXV remarkably inactivated the renin-angiotension-aldosterone system, and alleviated myocardial fibrosis and cardiomyocyte apoptosis, thus slowing down VR at post-AMI." (PMID 33618704, 2021). "In particular, both ANP and B-type natriuretic peptide appear to inhibit cardiac fibrosis by modulating renin-angiotensin-aldosterone system signaling." (PMID 32422879, 2020). "Inhibit cardiac fibrosis in renin-overexpressing hypertensive mice model." (PMID 36277752, 2022). "Furthermore, MRA treatment was only used in a small number of studies investigating survival, fibrosis and HW/BW and, overall, few studies used direct renin inhibitor and CCB treatment." (PMID 31673885, 2019). "Currently available in vitro assays have contributed to drug candidates targeting cardiac fibrosis, such as TGF-β inhibitors, renin–angiotensin–aldosterone system (RAAS) inhibitors, endothelin inhibitors, MMP inhibitors, relaxin, and others." (PMID 34305651, 2021). "Furthermore, the renin-angiotensin-aldosterone system (RAAS) pathway, Wnt signaling pathway, and adrenergic signaling pathway were also identified as up-regulated in IR-fibrosis HOs." (PMID 38693114, 2024). "However, direct effects of the renin-Ang II-AT1 cascade on lung injury independent of fibrosis cannot be excluded." (PMID 26494430, 2015).
malignant hypertension (20 papers, 2010 to 2025). Severe hypertension that is characterized by rapid onset of extremely high blood pressure and hypertension-mediated organ damage. "Malignant hypertension is associated with a rapid rise in blood pressure, pressure diuresis, severe renal vasoconstriction, ischemia, activation of renin–angiotensin–aldosterone system (RAS), microangiopathy, and hemolytic anemia." (PMID 40094833, 2025). "Chronic treatment with DOCA and salt results in volume retention, which causes malignant hypertension with a low plasma renin level." (PMID 40362650, 2025). "Malignant hypertension is in fact typically associated with an activation of the renin-angiotensin-aldosterone system (RAAS)." (PMID 27389397, 2016). "The pathogenesis in hypertensive emergencies is not fully understood, but rapidly increased blood pressure caused by the failure of arteriolar autoregulation is postulated to cause ED, renin-angiotensin-aldosterone system activation, and a pro-thrombotic state leading to organ injury." (PMID 33644125, 2020). "Conditional deletion of Connexin 40 in renin-expressing cells led to mislocalization of JG renin cells and excessive secretion of renin, resulting to malignant hypertension." (PMID 35710133, 2022). "Malignant hypertension was induced in Cyp1a1-Ren-2 transgenic rats by activation of the renin gene using indole-3-carbinol (I3C), a natural xenobiotic." (PMID 30054426, 2018). "After 5 weeks, mean arterial blood pressure was elevated to the same degree in malignant hypertension and non-malignant hypertension whereas plasma renin and aldosterone were significantly higher in malignant hypertensives." (PMID 27625610, 2016). "Once renal dysfunction occurs, the renin-angiotensin-aldosterone system (RAS system) becomes activated, causing a significant increase in blood pressure and changes in malignant hypertension." (PMID 24223652, 2013). "Strikingly high levels of plasma renin activity are typically observed accompanying malignant hypertension and it is almost certain that the renin-angiotensin system (RAS) plays a central role in the pathophysiology of SRC." (PMID 22738362, 2012). "Double transgenic rats (dTGR) harbouring human renin and human angiotensinogen genes develop malignant hypertension due to increased angiotensin II formation." (PMID 20721338, 2010). "Malignant hypertension due to a renin‐secreting tumor may need to be distinguished from a pheochromocytoma if alpha‐adrenergic blockade is ineffective." (PMID 26997629, 2016). "Double transgenic rats (dTGR) harbouring human renin and human angiotensinogen genes develop malignant hypertension, cardiac hypertrophy, renal damage, and endothelial dysfunction due to increased angiotensin II (Ang II) formation by the transfected human genes." (PMID 20721338, 2010). "At that stage, taking into account the laboratory exams, we needed to rule out several possible causes of malignant hypertension, including renal artery stenosis, and other insidious diseases such as phaeocromocytomas, lymphomas, and other renin-secreting masses." (PMID 27389397, 2016). "After dietary administration of indole-3-carbinol (I3C), the expression of the Cyp1a1 promoter is rapidly enhanced, with marked activation of Ren-2 renin gene in the liver, with subsequent increase in ANG II generation and development of ANG II-dependent malignant hypertension." (PMID 30054426, 2018).
Parkinson disease (20 papers, 2011 to 2025). A progressive degenerative disorder of the central nervous system characterized by loss of dopamine producing neurons in the substantia nigra and the presence of Lewy bodies in the substantia nigra and locus coeruleus. "Risk of Parkinson’s disease by type of renin-angiotensin system inhibitors and central nervous system penetration (N = 62,228)." (PMID 35308220, 2022). "Cox regression analysis on the association of Parkinson’s disease with renin-angiotensin system inhibitor use and confounding factors (N = 62,228)." (PMID 35308220, 2022). "Another interaction mechanism involves the angiotensin‐converting enzyme 2 receptor (ACE2), which mediates viral entry and is implicated in Parkinson's disease pathophysiology—renin–angiotensin system dysregulation, neuroinflammation, oxidative stress, and dopaminergic degeneration." (PMID 41181863, 2025). "Sensitivity analyses of adjusted hazard ratios of renin-angiotensin inhibitor use for Parkinson’s disease." (PMID 35308220, 2022). "Most recently, ACE-Is as renin–angiotensin system inhibitors were identified to be directly neuroprotective in a zebrafish model for Parkinson's disease." (PMID 35098999, 2022). "There are also studies that show that the renin-angiotensin system is involved in neurological disorders, including Alzheimer's and Parkinson's disease." (PMID 21247419, 2011). "The pathway analysis of these metabolites revealed their enrichment in Morphine addiction-related pathways, the cGMP-PKG signaling pathway, the regulation of lipolysis in adipocytes, renin secretion, Parkinson disease-related pathways, and the cAMP signaling pathway." (PMID 39629212, 2024). "We have previously obtained in rodents a considerable amount of data suggesting a major role for the brain renin–angiotensin system (RAS) in dopaminergic neuron degeneration and potentially in Parkinson’s disease." (PMID 22407459, 2013). "The tissue renin–angiotensin system (RAS) has been shown to be involved in prooxidative and proinflammatory changes observed in aging and aging-related diseases such as dopaminergic degeneration in Parkinson’s disease (PD)." (PMID 35204211, 2022).
diabetic retinopathy (19 papers, 2014 to 2025). "One of the factors that have recently been implicated more prominently in the pathogenesis of diabetic retinopathy is the renin-angiotensin system (RAS)." (PMID 33062311, 2020). "Diabetic retinopathy was more frequently observed and more renin–angiotensin system (RAS) inhibitors were administered in the albuminuria group than in the normoalbuminuria group." (PMID 28912839, 2017). "Dysfunction of renin-angiotensin system (RAS) contributes to the pathogenesis of diabetic retinopathy (DR)." (PMID 24968134, 2014). "In conclusion, the lack of effect of HRP on top of aliskiren, and the Ang II-dependency of the ocular effects of prorenin in vitro, argue against the combined application of (P)RR blockade and renin inhibition in diabetic retinopathy." (PMID 24968134, 2014). "Additionally, in treating diabetic retinopathy, engineered Lactobacillus paracasei secreting angiotensin-converting enzyme 2 reduced inflammation and oxidative stress within the renin-angiotensin system, improving diabetic retinopathy outcomes." (PMID 39233526, 2024). "In an extension of our research regarding the relationship between the renin-angiotensin system and diabetic retinopathy, we found that in comparison with other diseases, tryptase activity is higher in the vitreous of ERM and MH, and that chymase activity is higher in the vitreous of MH." (PMID 30794552, 2019). "In view of the vascular actions of angiotensin II, an intraocular renin-angiotensin system may play a role in diabetic retinopathy." (PMID 30460043, 2018). "In the Renin-Angiotensin System Study (RASS), enalapril and losartan decreased diabetic retinopathy progression." (PMID 36830828, 2023). "Both systemic and local RAAS are implicated in the pathogenesis of retinopathy and all components of the RAAS are expressed in retina with highly elevation of renin, ACE, Ang II and AT1R in patients with diabetic retinopathy." (PMID 26310144, 2015). "The beneficial effects of anti-hypertensive medications that target the renin-angiotensin-aldosterone system (RAAS) in DR and DME have been evaluated in several clinical trials, such as the Diabetic Retinopathy Candesartan Trials (DIRECT) and Renin-Angiotensin System Study (RASS)." (PMID 29649995, 2018).
hyperthyroidism (19 papers, 2008 to 2025). Overactivity of the thyroid gland resulting in overproduction of thyroid hormone and increased metabolic rate. "Hyperthyroidism can cause hypertension through increased cardiac output as well as increased levels of renin, angiotensin, and aldosterone." (PMID 37490265, 2023). "Hyperthyroidism is associated with results in increased glomerular filtration rate as well as increased renin-angiotensin-aldosterone activation." (PMID 33754657, 2021). "In hyperthyroidism, intra-glomerular hypertension, consequent hyperfiltration, increased production of free radicals, and increased renin–angiotensin–aldosterone system are risk factors for albuminuria." (PMID 32277301, 2020). "In this study we have observed that hyperthyroidism has caused an upsurge in the levels of serum renin, angiotensin II, and aldosterone, but the changes were of no significance when they were compared to the normal rats." (PMID 31396276, 2019). "Further laboratory studies revealed an elevated plasma aldosterone level with low renin activity, and thyroid function tests were consistent with mild primary hyperthyroidism." (PMID 35702451, 2022). "Hyperthyroidism leads to increased glomerular filtration rates and activation of the renin-angiotensin-aldosterone system." (PMID 34046503, 2021). "The serum levels of renin, angiotensin I and II were increased after inducing hyperthyroidism by L‐thyroxine." (PMID 31579950, 2019). "An increasing number of studies have shown that vitamin D can lower blood pressure by inhibiting the renin-angiotensin-aldosterone system, and preventing secondary hyperthyroidism simultaneously, providing anti-inflammatory benefits and protecting blood vessels." (PMID 39554649, 2024). "Increased plasma renin activity has also been demonstrated in patients with hyperthyroidism." (PMID 35239685, 2022). "Hyperthyroidism also activates the renin-angiotensin-aldosterone system (RAAS)." (PMID 35239685, 2022). "Renin-angiotensin-aldosterone system (RAAS) is activated by thyroid hormones in hyperthyroidism." (PMID 35330837, 2022). "Hypo and hyperthyroidism influence the classic main components of the renin-angiotensin system." (PMID 30555423, 2018). "The association between IMT and endogenous or exogenous thyroid hyperfunction is regarded as biologically plausible because there is a known link between hyperthyroidism and peripheral vasodilatation, which leads to a decrease in renal perfusion and activation of the renin-angiotensin system." (PMID 19014658, 2008). "Hyperthyroidism results in an increased glomerular filtration rate (GFR) by about 18–25% due to increased renal blood flow and activation of renin-angiotensin-aldosterone system (RAAS)." (PMID 37490265, 2023). "Evidence from human and animal studies demonstrates that the renin-angiotensin system (RAS) plays a crucial role in vascular function and also mediates some of cardiovascular effects found during hyperthyroidism." (PMID 23637941, 2013).